CD4 (CD4 molecule)
Diseases named in the same sentence as CD4 in open-access papers (continued):
Sharing a sentence is not in itself a finding about the gene and the disease.
tumor (continued). "The vaccinated mice showed significant inhibition of tumor growth, which was associated with strong CD4+ and CD8+ T cell responses specific to the tumor antigens targeted by the vaccine." (PMID 37626903, 2023). "The identification of CD4+ TCR specific for KRAS mutations provides the foundation for applying the CD4+ T-cell immunity to the adoptive transfer therapy and deepens the mechanism of CD4+ T cells in human anti-tumor immunity." (PMID 37287989, 2023). "Significantly, the DC peptide vaccine-treated animals exhibited increased levels of CD8 T lymphocytes in the TME whereas the level of CD4 T lymphocytes and tumour-associated macrophages remained unchanged." (PMID 36841868, 2023). "Enrichment of CD4+ T cells associated with these two pathways in the tumor microenvironment generally leads to a better immune response and a better prognosis." (PMID 37965307, 2023). "Our study presented that PD-L1 expression was associated with CD8 TILs and CD4 TILs in the tumor immune microenvironment (X2 = 11.238, p = 0.003; X2 = 12.614, p = 0.001)." (PMID 36836455, 2023). "Patients in the high-risk set had significantly lower proportions of tumor-infiltrating CD4 memory resting T cells, M2 macrophages and resting mast cells." (PMID 36674979, 2023). "The receptor is able to regulate the anti-tumor response through CD4+ Tregs that are associated with tumor burden in OC patients." (PMID 37446039, 2023). "FoxP3+ T cells are usually associated with a negative regulatory function (Treg) over CD4+ Th cells, and their presence in the tumor microenvironment often indicates an immunosuppressive function toward anti-tumor T cells." (PMID 36993983, 2023). "These cells are considered to be key inducers of CD4+ T helper cell responses for efficient presentation of MHC II-associated tumor antigens." (PMID 36949244, 2023). "Here, we describe a mechanism whereby a small number of CD4+ T cells is sufficient to eradicate MHC-deficient tumours that escape direct CD8+ T cell targeting." (PMID 37316667, 2023). "Thorough analysis of immune cell infiltration showed that various anti-tumor immune cells, such as B cells and CD4+ T cells, are elevated in the low-risk subgroup, and this aligns with earlier research findings." (PMID 37941546, 2023). "The results showed that high IERS was associated with high tumor purity, high activated CD4 memory cells, M0 and M1 macrophage abundance, high PD-L1, CXCL10, and GZMB expression." (PMID 36936970, 2023). "Effector CD4+ T cells then provoke tumor-associated macrophages (TAMs/M1) and natural killer cells (NK) in the tumor microenvironment, leading to the mediation of local antitumor immunity with the release of pro-inflammatory molecules." (PMID 37111629, 2023). "In particular, infiltration of cytotoxic CD8+ T lymphocytes, CD4+ T lymphocytes, and tumor-associated macrophages (TAM) predicted favorable results." (PMID 37695742, 2023). "It has been reported that a higher number of CD4 + Th1 is associated with tumor suppression while a higher number of CD4 + Th2 cells is associated with oral tumor growth." (PMID 37221555, 2023). "HCFC1 expression showed a significant positive association with B cell memory, T cell CD4 memory, macrophage M0, and a significant positive association with immune checkpoint-related gene expression in the tumor microenvironment." (PMID 37283799, 2023). "For instance, tumor-associated macrophages (TAMs) and CD4(+) CD25(+) Foxp3(+) regulatory T cells (Tregs) are associated with poor prognosis in patients with HCC." (PMID 37133437, 2023). "Accordingly, a close association was identified between these genes and tumor-infiltrating immune cells, including natural killer (NK) cells, neutrophils, and CD4+ T cells in patients with CC." (PMID 38327905, 2023). "Obviously, tumor‐associated macrophages and inflammation were detected at high levels, including T cells CD4 memory activated, B cell memory, and dendritic cells activated." (PMID 37555363, 2023).
tumor (continued). "The expression of the EBV signaling protein LMP1 in B lymphocytes triggered CD4+ T cell responses against various tumor-associated antigens." (PMID 37063862, 2023). "At the center stage of adaptive immunity, CD4+ T cells are extensively implicated in anti-tumor responses." (PMID 38062068, 2023). "This is contradictory to the fact that high levels of tumor-infiltrating CD4/CD8 T cells usually associated with good outcome." (PMID 37592010, 2023). "Again, ovalbumin-specific OT-II TCRtg CD4+ T cells were able to eradicate ovalbumin-expressing MHC-deficient HCmel12 Jak1-KO tumours, whereas ovalbumin-specific OT-I TCRtg CD8+ T cells were ineffective." (PMID 37316667, 2023). "Tumor regression was observed in all lesions after transfusion of ERBB2IP mutation-specific CD4+ T cells into the patient." (PMID 37287989, 2023). "It has been postulated that NLRP3 signaling within tumor-associated macrophages (TAMs) drives the polarization of CD4+ T cells in the tumor microenvironment toward an immune-suppressive phenotype." (PMID 38018872, 2023). "This association between higher TIL levels and pCR has been confirmed in ICORG 10-05, with <5% residual tumour and reduced tumour-associated CD4+ and CD8+ T cells after one cycle of therapy in the pCR cohort." (PMID 37507543, 2023). "Tumor-associated resting CD4 memory T cells is the main immune component of many tumors, which can promote tumor progression." (PMID 38196829, 2023). "Increased levels of tumor-infiltrating lymphocytes (TILs), such as CD4+T cells and CD8+T cells, are associated with immunotherapy response and longer survival." (PMID 36798829, 2023). "In the early phase of cancer development, neutrophils exert anticancer activity by reactive oxygen species (ROS) that cause tumour cell lysis and by the production of co-stimulatory molecules that enhance the proliferation of CD4+ and CD8+ T lymphocytes." (PMID 36928373, 2023). "On the other hand, accumulation of CD4+ T cells in the PCa tumour microenvironment was associated with a poor survival." (PMID 38137361, 2023). "In inner tumor areas a direct association of CD4+, FOXP3+ TILs, and FOXP3+/CD8+ ratio with VSA t2 was noted (p = 0.008, 0.02, and 0.05, respectively)." (PMID 36586079, 2023). "PD-1 blockade restores helper activity of exhausted CD4+ tumour-infiltrating lymphocytes (TILs) in vitro associated with enhanced IFN-γ production." (PMID 37957274, 2023). "The combination of local radiation and metformin in LuM1, a highly lung metastatic subclone of colon 26, injected BALB/c mice also resulted in delay in tumor growth associated with enhanced IFN-γ production of the splenic CD4+ and CD8+ T cells." (PMID 36614197, 2023). "CD4+ T cells cause tumor regression through an IFN‐c‐dependent mechanism, which occurs by recruiting macrophages and/or eosinophils." (PMID 37755128, 2023). "High CD4+ levels in the tumor region and total regions were significantly associated with better survival (P<0.05)." (PMID 37090736, 2023). "Both minigenes encoding the tumor variant MYLKD>N showed reproducible low-level depletion after coculture with CD4+ TIL, and this variant was therefore considered a putative screen hit." (PMID 36593398, 2023). "Defective STAT4‐induced lymphatic metastasis and immune suppression via increased lymph‐angiogenesis with elevated VEGFA expression and decreased production of IFN‐γ with CD4+ cell dependent in STAT4 deficient tumor bearing mice." (PMID 38107057, 2023). "IFN-γ also inhibits the function of certain suppressive immune cells, including tumor‐associated macrophages (TAMs), myeloid‐derived suppressor cells (MDSCs), and regulatory CD4+ T cells (Tregs)." (PMID 37205112, 2023). "Adenosine receptors are broadly expressed by tumor-infiltrated immune cells, including suppressive tumor-associated macrophages and CD4+ regulatory T cells, as well as effector CD4+ T cells and CD8+ cytotoxic T lymphocytes." (PMID 37834375, 2023).
tumor (continued). "The analysis of tumor-infiltrating immune cells in the TCGA-LAML patient cohort showed higher tumor infiltration levels of memory-activated CD4 T cells, Tregs, and monocytes in the high-risk group." (PMID 37388937, 2023). "Previous studies found that the therapeutic benefit of the UNITETM platform is associated with enhanced tumor-infiltrating CD4 and CD8 T cells." (PMID 37711623, 2023). "Infiltration of CD4+Tregs in TME suppresses local anti-tumor immune responses and is associated with poor prognosis in various types of cancer." (PMID 38250084, 2023). "CD4+ T cells are often initiators of an anti-tumor response and are associated with a favorable response to immunotherapy." (PMID 37608898, 2023). "Further, a co-culture of tumor organoids, tumor associated macrophages and CD4+ T cells even further induced an invasive phenotype that appears dependent on IL-4 signaling." (PMID 37091337, 2023). "The Th1 cytokines produced by CD4 cells induce antigen-presenting cells (APCs) to cross-present tumor associated antigens and are critical factors in the acquisition of antitumor immunity." (PMID 37868996, 2023). "scRNAseq profiling further confirmed an association between tumor control and an intratumoral CD4 CTL subset exhibiting effector phenotype and clonal expansion." (PMID 37185301, 2023). "This study shows that the MHC class II expression in tumor cells and the associated CD4+ T-cell responses behave differently in a variety of tumor entities as well as in tumors with a shared etiology." (PMID 37046620, 2023). "Previous studies have found that higher levels of tumor-infiltrating CD4(+) T, CD8(+) T, were significantly associated with longer survival." (PMID 37710166, 2023). "The results showed that LFA-1 was highly correlated with Foxp3 in SKCM, and the LFA-1 expression level is negatively associated with tumor cells purity and positively associated with the infiltration of CD4 + T cells and CD8 + T cells." (PMID 37723552, 2023). "What is more, expression of ITGA5 was associated with an increased infiltration to the tumor core of CD4 + T cells, macrophages, neutrophils and dendritic cells." (PMID 37284199, 2023). "It has been shown that CAP is associated with more active tumor-infiltrating immune cells such as dendritic cells, CD4 and CD8 T cells and NK cells, which lead to the control or rejection of the implanted tumors." (PMID 36742298, 2023). "In the first, the elimination phase, immune cells, such as CD8+, CD4+, NK cells, and macrophages, identify tumor-associated antigens resulting in the elimination of tumor cells." (PMID 37662676, 2023). "T lymphocytes, including CD8+ cytotoxic T lymphocytes (CTLs) and CD4+ Th1 cells, natural killer (NK) cells, and DCs are major players in tumor-associated immune responses." (PMID 37175993, 2023). "A high immune score is associated with enriched tumor-infiltrating immune cells, including CD4 + T cells, CD8 + -T cells, regulatory T (Treg) cells, and TAMs." (PMID 37821959, 2023). "Vaccine-induced neoantigen-specific Th1 CD4+ T cells in the tumor were associated with decreased Tregs." (PMID 38063199, 2023). "Here the authors show that reduced levels of methionine are associated with PD1 upregulation in CD4+ T cells and that methionine supplementation promotes CD4+ T cell dependent anti-tumor immune responses." (PMID 37147330, 2023). "CD4+ T cells were significantly association with all the other tumor-associated immune cells (TAIs) including CD8, CD68 and CD206 positive cells." (PMID 37405518, 2023). "The differentiation of CD4+ T cells is closely associated with tumor prognosis, and immunotherapy effects, playing an important role in tumor immunotherapy." (PMID 38062068, 2023). "This treatment was also associated with an improvement in the tumor immune microenvironment, as shown by increases in CD4+ and CD8+ T cells and a decrease in MDSCs." (PMID 36632215, 2023).
tumor (continued). "The tumor-suppressing capability of the GPR15-GPR15L axis was associated with a significant influx of CD4+ and CD8+ T cells into the tumor, in particular IFNγ or TNFα secreting T cells." (PMID 38074634, 2023). "The intratumoral CD4 T cell subset associated with tumor regression expressed multiple cytotoxic markers and exhibited clonal expansion." (PMID 37185301, 2023). "The expression of GLIS1 exhibited a notable inverse association with tumor purity and was positively correlated with the infiltration of various immune cells in PCa, including B cells, DC, CD4+ T cells, CD8+ T cells, macrophages, and neutrophils." (PMID 38203661, 2023). "CD4+ T lymphocyte deficiency leads to transcriptomic alterations in tumor-associated vascular ECs, resulting in modifications in the pathways or genes known to regulate vascular normalization." (PMID 38193080, 2023). "Activated CD4 + T-cells colocalize with tumor-associated endothelial cells, causing transcriptomic alterations in these cells." (PMID 37907742, 2023). "Immune gene markers of B cell, T cell (general), CD8 + cell, CD4 + cell, tumor-associated macrophage (TAM), M1 and M2 macrophage, neutrophil, natural killer cell (NK) cell, DC, Th1/2/fh/17cell, Treg, and T cell exhaustion in HCC were assessed." (PMID 37968735, 2023). "Immune cells of the tumor microenvironment are associated with the efficacy of immunotherapy, including CD4 + T cells CD8 + T cells, NK cells, and macrophage cells." (PMID 37558987, 2023). "We observed that IL‐6 was secreted specifically by both CD8+ and CD4+ CAR T cells in response to stimulation through the CAR by tumor cells expressing the EGFRvIII mutation." (PMID 36890859, 2023). "This article describes a mechanism through which CD4+ T cells can eradicate MHC-deficient tumours that escape direct CD8+ T cell targeting and thereby complement the activity of CD8+ T cells and natural killer cells to advance cancer immunotherapies." (PMID 37316667, 2023). "Tumor microenvironment analysis showed that the high-risk group had significantly more resting memory CD4 T cells, M0 macrophages, and activated dendritic cells and fewer naïve B cells, plasma cells, and CD8 T cells than the low-risk group (both P < 0.05)." (PMID 36871072, 2023). "For example, 6-gingerol treatment of tumor-bearing mice caused massive infiltration of CD4+ and CD8+ T cells and B220+ B cells, which inhibited tumor growth in mice." (PMID 37816138, 2023). "This was contradictory to the fact that high levels of tumor infiltrating CD4/CD8 T cells were generally associated with better prognosis." (PMID 37592010, 2023). "Tumours with high Fusobacterium relative abundance were found to be associated with significantly greater proportions of CD4 + lymphocytes (p = 0.031) and M1 macrophages (p = 0.006), whilst M2 macrophages (p = 0.043) were under-represented across this group." (PMID 37171483, 2023). "cDC1s can present tumor-associated antigens (TAAs) from apoptotic tumor cells to CD4+ and CD8+ T cells, thus inducing potent T-cell-mediated immune responses." (PMID 37563648, 2023). "A striking correlation of TERT expression in our study was a higher estimate of tumor-infiltrating CD4+ T cells, which were previously associated with improved clinical outcome of ICI therapy." (PMID 37418389, 2023). "The IFN-γ production rate by CD4+ T cells is αy=9 (pg/mL)(day−1)(cell−1)(cell−1), while the loss rate of tumor-suppressing cytokines is γc=34 day−1." (PMID 36766849, 2023). "In parallel, we assessed the frequency of peripheral and tumor-associated CD4+ T cells and Treg in KC versus WT mice." (PMID 38098486, 2023). "The transformation of CD4+ T cells into Tregs is a continuous process associated with tumor development." (PMID 37187731, 2023). "A high percentage (>75%) of tumor-infiltrating CD4+ T cells was associated with decreased freedom from treatment failure (FFTF)." (PMID 37372147, 2023).
tumor (continued). "Targeting specific cells within the TME, such as eosinophils, tumour-associated macrophages, cancer-associated fibroblasts, tumour-infiltrating lymphocytes, and regulatory CD4+/CD8+ T cells, can enhance anti-tumour immunity in breast cancer." (PMID 37448962, 2023). "For example, a high CD4 + /CD8 + cell count ratio of infiltrating lymphocytes in the tumor was associated with a poor prognosis, and GBM with a high mutational burden responded significantly to the administration of ICI nivolumab." (PMID 37071249, 2023). "The infiltration of CD8+ T cells and CD4+ Th1 cells at the tumor site is a hallmark of a favorable tumor prognosis, due to their production of the cytokines IFNγ and TNFα, which can effectively induce the cell cycle of tumor cells to arrest in the G1/G0 phase." (PMID 37545500, 2023). "Key immune-cell populations in the TME include tumour-associated macrophages (TAMs), CD4-expressing or ‘positive’ (CD4+) and CD8-positive (CD8+) T-cell subsets, B-cells, plasma cells, eosinophils, and mast cells." (PMID 37958391, 2023). "Expression of co-inhibitory markers such as PD-1 is a hallmark of both tumor-reactive CD4+ and CD8+ T cells in the TME." (PMID 37400675, 2023). "The activation of CD8+ T cells with specificity for TAAs or TSAs leads to cytotoxic reactions that cause tumour cell death, while activated CD4+ T cells produce cytokines." (PMID 37631324, 2023). "DLBCL with CREBBP mutations shows depletion of tumor-infiltrating CD4+ T cells, while EP300 mutation is associated with M2 macrophage polarization, which induces an immune-suppressive TME." (PMID 36765793, 2023). "We show that T helper type 1 cell-directed CD4+ T cells and innate immune stimulation reprogramme the tumour-associated myeloid cell network towards interferon-activated antigen-presenting and iNOS-expressing tumouricidal effector phenotypes." (PMID 37316667, 2023). "Tumoural PD-L1 expression was associated with a denser intratumoural regulatory T cell infiltrated as evidenced by higher CD4+/FOXP3+ cell density (40.8 vs. 12.3 cells/mm2, p = 0.001)." (PMID 37274775, 2023). "A univariate PFS analysis revealed that high tumor infiltration of B cells, CD4 T cells, and CD8 T cells was significantly associated with improved PFS (P < 0.05), and a similar trend was observed in patients with high TERT expression level (P = 0.079)." (PMID 36909826, 2023). "Analysis of tumor immune cell infiltration revealed that AGRN is closely associated with memory CD4+T cells activated, monocytes, plasma cells, Tfh cells, NK cells activated, mast cells resting, and DCs resting." (PMID 37841281, 2023). "CD4+ T cells secrete different cytokine profiles that are closely associated with anti-tumor immunity in various cancers." (PMID 37834375, 2023). "Although we did not discover any correlation between total CD68+ TAMs and total CD3+ T cell as well as its CD4+ and CD8+ subgroups, we found that CD206+ TAMs were closely associated with CD4+ tumor-infiltrating T lymphocytes." (PMID 36864443, 2023). "This substantial discovery elucidates how CD4+ T cells indirectly eradicate tumor cells through collaboration with tumor-associated myeloid cells and stimulation of innate immune cells." (PMID 38077321, 2023). "The high-risk group had a significantly higher degree of immune infiltration, with more CD8+T cells, tumor-associated fibroblasts, macrophages, monocyte infiltration, and less CD4+T cell infiltration, as compared with the low-risk group." (PMID 37180113, 2023). "Being a subset of CD4+ helper T cells, Follicular helper T cells promote tumor-associated lymphocyte activity, enhancing immune responses." (PMID 37351275, 2023). "With regard to tumor infiltrating immune cells analysis, the risk score was negatively correlated with infiltration levels of CD4+ and CD8+T cells, which played a key role in immunotherapy." (PMID 37098532, 2023).